RAP1GDS1 (Rap1 GTPase-GDP dissociation stimulator 1)
Description:
Acts as a GEF (guanine nucleotide exchange factor) for the Rho family of small GTP-binding proteins (G proteins) that stimulates the dissociation of GDP to enable subsequent binding of GTP. Additionally, appears to chaperone the processing and/or trafficking of small GTPases containing a C-terminal polybasic region independently of GEF activity. Targets include RAP1A/RAP1B, RHOA, RHOB, RHOC, RAC1 and KRAS. Regulates mitochondrial dynamics by controlling RHOT function to promote mitochondrial fission during high calcium conditions. Able to promote the Ca(2+) release from the endoplasmic reticulum via both inositol trisphosphate (Ins3P) and ryanodine sensitive receptors leading to a enhanced mitochondrial Ca(2+) uptake. [Isoform 1]: Acts as a GEF (guanine nucleotide exchange factor) for unprenylated RHOA. Chaperones the entry and passage of small GTPases through the prenylation pathway. Recognizes the last amino acid in the GTPase C-terminal CAAX motif with a preference for 'Leu' over 'Met', indicating involvement in the geranylgeranylation pathway. [Isoform 2]: Acts as a GEF (guanine nucleotide exchange factor) for prenylated RHOA. Acts as a GEF for RHOC. Chaperones the downstream trafficking and/or processing of small newly prenylated GTPases. Escorts RAC1 to the nucleus.
Synonyms: SMGGDS; GDS1
Tractability: Small molecule: a structure with a bound ligand is known. PROTAC: ubiquitination databases record sites on it; its protein half-life has been measured.
Gene: Protein-coding gene on chromosome 4 (98,261,243 to 98,443,864, forward strand). Ensembl gene ENSG00000138698.
Subcellular location: Cytoplasm, cytosol; Endoplasmic reticulum; Mitochondrion; Nucleus
Subcellular location (Human Protein Atlas): Cytosol
Pathways (Reactome):
Signal Transduction: RHOT1 GTPase cycle; RHOT2 GTPase cycle
Gene Ontology:
Molecular function: guanyl-nucleotide exchange factor activity; protein binding
Biological process: CAAX-box protein maturation; negative regulation of endoplasmic reticulum calcium ion concentration; positive regulation of mitochondrial calcium ion concentration; protein localization to nucleus; regulation of mitochondrion organization; myosin filament assembly; vascular associated smooth muscle contraction
Cellular component: cytosol; endoplasmic reticulum; extracellular exosome; mitochondrion; nucleus
Genetic constraint (gnomAD): Loss-of-function variants: 33 observed, 67.37 expected, observed/expected ratio (o/e) 0.49, 90% interval 0.37 to 0.65. The upper end of that interval is the gene's LOEUF score, 0.65, which puts it in group 2 of 6, group 1 being the genes least tolerant of losing a copy. Missense variants: 658 observed, 709.38 expected, observed/expected ratio (o/e) 0.93, 90% interval 0.87 to 0.99. Synonymous variants: 227 observed, 247.68 expected, observed/expected ratio (o/e) 0.92, 90% interval 0.82 to 1.02.
Cancer hallmarks: proliferative signalling (promotes); invasion and metastasis (promotes); invasion and metastasis
Homologues: Orthologues: chimpanzee RAP1GDS1 (99% identical), macaque RAP1GDS1 (99% identical), dog RAP1GDS1 (98% identical), rabbit RAP1GDS1 (97% identical), pig RAP1GDS1 (97% identical), rat Rap1gds1 (96% identical), mouse Rap1gds1 (95% identical), guinea pig RAP1GDS1 (95% identical), tropical clawed frog rap1gds1 (86% identical), zebrafish RAP1GDS1 (59% identical), Drosophila melanogaster vimar (29% identical).
Diseases named in the same sentence as RAP1GDS1 in open-access papers:
RAP1GDS1 is named in the same sentence as 15 diseases in open-access papers, as found by Europe PMC text mining. Sharing a sentence is not in itself a finding about the gene and the disease. The quoted sentences say what the papers report.
developmental delay (2 papers, 2022 to 2023). "In support of this finding, a loss-of-function RAP1GDS1 mutant was identified in patients that was associated with developmental delay, hypotonia and cognitive deficits, indicating that RAP1GDS1 may play an important role in development." (PMID 37061660, 2023). "RAP1GDS1 (MIM 179502) has recently been linked to intellectual disability, global developmental delay, and hypotonia, but lacks a clear link with heart development or CHD." (PMID 35885997, 2022).
neuroblastoma (2 papers, 2016 to 2023). Neuroblastoma (NB) is the most common solid, extracranial childhood tumor. "Using the SK-N-SH human neuroblastoma cell line, we observed a similar effect of RAP1GDS1 overexpression and RNAi on mitochondrial function, suggesting that the RAP1GDS1 effect on mitochondria is not cell-type specific." (PMID 37061660, 2023). "Moreover, we tested the RAP1GDS1 shRNA in another human cell line, the SH-SY5Y neuroblastoma cells." (PMID 27716788, 2016).
T cell acute lymphocytic leukemia (2 papers, 2010 to 2023). "It was reported that translocation fusion of the NUP98 and RAP1GDS1 genes was recurrent in T-cell acute lymphocytic leukemia." (PMID 21114830, 2010).
pancreatic cancer (1 paper, 2025). "Utilizing XGBoost and RF, we pinpointed 10 genes closely related to pancreatic cancer, culminating in the identification of RAP1GDS1, TOP2A, ADK, POLL, CD44, and CD4 as pivotal genes linked to hypoxia in pancreatitis." (PMID 40787634, 2025).
pancreatitis (1 paper, 2025). Inflammation of the pancreas. "Further investigations, including differential expression analysis and machine learning techniques, revealed six significant diagnostic markers for pancreatitis: RAP1GDS1, TOP2A, ADK, POLL, CD44, and CD4." (PMID 40787634, 2025). "We then conducted qRT-PCR on serum samples from five pancreatitis patients and five healthy controls to examine the expression levels of RAP1GDS1, TOP2A, ADK, POLL, CD44, and CD4." (PMID 40787634, 2025). "In our study, we identified key hypoxia-related genes—RAP1GDS1, TOP2A, ADK, POLL, CD44, and CD4—in pancreatitis samples using methods such as WGCNA, XGBoost, and RF algorithms." (PMID 40787634, 2025).
prostate carcinoma (1 paper, 2024). A carcinoma that arises from epithelial cells of the prostate gland. "A study in prostate cancer cells demonstrated high expression of RAP1GDS1 in cells under hypoxia and postulated that targeting it and similar CLK kinases may provide benefit in the treatment of cancers in which tumour hypoxia contributes to resistance to therapy." (PMID 38391955, 2024).
cancer (7 papers, 2010 to 2025). A tumor composed of atypical neoplastic, often pleomorphic cells that invade other tissues.
tumor (5 papers, 2009 to 2024). "The top 5 proteins exclusively detected in tumor in ≥ 90% of the cases included CD68 (a macrophage marker), Optineurin (OPTN), Nuclear receptor coactivator 5 (NCOA5), RAP1GDS1 (Rap1 GTPase-GDP dissociation stimulator 1) and Stromal cell derived factor 2 like 1 (SDF2L1)." (PMID 36508875, 2023). "Bergom and colleagues more closely analyzed the tumor suppressive mechanisms of DIRAS-1 and showed that DIRAS-1 binds to the noncanonical guanine nucleotide exchange factor SmgGDS (Rap1 GTPase-GDP dissociation stimulator 1 = RAP1GDS1) and acts similarly to a dominant-negative small GTPase." (PMID 34680261, 2021). "Negative correlations across those tumor types were observed in four target genes (ARPC2, CFL1, PLIN3, RAP1GDS1)." (PMID 39201394, 2024).
infection (2 papers, 2019 to 2020). The state of being infected such as from the introduction of a foreign agent such as serum, vaccine, antigenic substance or organism. "In addition, a number of genes associated with GTPase activities, which included GIMAP2, RACGAP1, AGBL5 and RAP1GDS1, were down-regulated during the early phase of infection." (PMID 30789917, 2019).
metabolic disease (1 paper, 2025). A congenital disorder (due to inherited enzyme abnormality) or acquired (due to failure of a metabolically important organ) disorder resulting from an abnormal metabolic process. "Our findings indicate that RAP1GDS1 is involved in rRNA modification in both the nucleus and cytosol, along with constitutive signaling by EGFRVIII and metabolic diseases." (PMID 40787634, 2025).
RAP1GDS1 also shares sentences with these, for which no sentence is quoted: Intellectual disability (2 papers); Alfadhel syndrome (1); breast carcinoma (1); cognitive deficits (1); syndromic intellectual disability (1).